CYP3A5 (cytochrome P450 family 3 subfamily A member 5)
Description:
A cytochrome P450 monooxygenase involved in the metabolism of steroid hormones and vitamins. Mechanistically, uses molecular oxygen inserting one oxygen atom into a substrate, and reducing the second into a water molecule, with two electrons provided by NADPH via cytochrome P450 reductase (NADPH--hemoprotein reductase). Catalyzes the hydroxylation of carbon-hydrogen bonds. Exhibits high catalytic activity for the formation of catechol estrogens from 17beta-estradiol (E2) and estrone (E1), namely 2-hydroxy E1 and E2. Catalyzes 6beta-hydroxylation of the steroid hormones testosterone, progesterone, and androstenedione. Catalyzes the oxidative conversion of all-trans-retinol to all-trans-retinal, a rate-limiting step for the biosynthesis of all-trans-retinoic acid (atRA). Further metabolizes all trans-retinoic acid (atRA) to 4-hydroxyretinoate and may play a role in hepatic atRA clearance. Also involved in the oxidative metabolism of xenobiotics, including calcium channel blocking drug nifedipine and immunosuppressive drug cyclosporine.
Synonyms: PCN3; P450PCN3; CP35; CYPIIIA5
Tractability: Small molecule: an approved drug acts on it; a structure with a bound ligand is known; a high-quality ligand is known; it belongs to a druggable protein family. Antibody: UniProt places it where antibodies can reach, with medium confidence. PROTAC: its protein half-life has been measured; a small molecule that binds it is known.
Target class: Cytochrome P450 3A5; Cytochrome P450 family 3; Cytochrome P450; Cytochrome P450 family 3A; Enzyme
Safety:
Unwanted effects reported when the protein is acted on. In parentheses: how it was acted on, where the effect was seen, and who reports it.
adverse events (source: ClinPGx)
calcineurin-inhibitor induced hepatic toxicity (source: ClinPGx)
degree of muscle damage (source: ClinPGx)
dose reductions due to toxicity (source: ClinPGx)
hyperlipidemia (source: ClinPGx)
infections (source: ClinPGx)
leukopenia or neutropenia (source: ClinPGx)
myalgia (source: ClinPGx)
myalgia and degree of muscle damage (source: ClinPGx)
nephrotoxicity (source: ClinPGx)
neurotoxicity (source: ClinPGx)
opioid use disorder (source: ClinPGx)
renal dysfunction (source: ClinPGx)
response to treatment (source: ClinPGx)
somnolence (source: ClinPGx)
systolic and diastolic blood pressure (source: ClinPGx)
transplant rejection (source: ClinPGx)
Gene: Protein-coding gene on chromosome 7 (99,648,194 to 99,679,997, reverse strand). Ensembl gene ENSG00000106258.
Subcellular location: Endoplasmic reticulum membrane; Microsome membrane
Subcellular location (Human Protein Atlas): Cytosol; Vesicles
Pathways (Reactome):
Metabolism: Aflatoxin activation and detoxification; Xenobiotics
Gene Ontology:
Molecular function: estrogen 16-alpha-hydroxylase activity; estrogen 2-hydroxylase activity; oxidoreductase activity; oxidoreductase activity, acting on paired donors, with incorporation or reduction of molecular oxygen, reduced flavin or flavoprotein as one donor, and incorporation of one atom of oxygen; protein binding; retinoic acid 4-hydroxylase activity; testosterone 6-beta-hydroxylase activity; monooxygenase activity; oxygen binding; heme binding; iron ion binding; oxidoreductase activity, acting on paired donors, with incorporation or reduction of molecular oxygen
Biological process: alkaloid catabolic process; estrogen metabolic process; lipid hydroxylation; oxidative demethylation; retinoic acid metabolic process; steroid metabolic process; xenobiotic catabolic process; aflatoxin metabolic process; xenobiotic metabolic process; retinol metabolic process
Cellular component: endoplasmic reticulum membrane; intracellular membrane-bounded organelle
Genetic constraint (gnomAD): Loss-of-function variants: 38 observed, 48.44 expected, observed/expected ratio (o/e) 0.78, 90% interval 0.6 to 1.03. The upper end of that interval is the gene's LOEUF score, 1.03, which puts it in group 4 of 6, group 1 being the genes least tolerant of losing a copy. Missense variants: 510 observed, 598.49 expected, observed/expected ratio (o/e) 0.85, 90% interval 0.79 to 0.92. Synonymous variants: 190 observed, 218.45 expected, observed/expected ratio (o/e) 0.87, 90% interval 0.77 to 0.98.
Homologues: Orthologues: chimpanzee CYP3A5 (97% identical), dog CYP3A26 (79% identical), dog CYP3A12 (78% identical), dog CYP3A26 (76% identical), pig CYP3A29 (75% identical), rat Cyp3a9 (75% identical), mouse Cyp3a13 (75% identical), mouse Cyp3a11 (73% identical), mouse Cyp3a41a (72% identical), mouse Cyp3a41b (72% identical), rat Cyp3a23-3a1 (72% identical), mouse Cyp3a25 (71% identical), and 18 more. Paralogues in human: CYP3A4 (84% identical), CYP3A7 (82% identical), CYP3A43 (76% identical).
Diseases named in the same sentence as CYP3A5 in open-access papers:
CYP3A5 is named in the same sentence as 164 diseases in open-access papers, as found by Europe PMC text mining. Sharing a sentence is not in itself a finding about the gene and the disease. The quoted sentences say what the papers report.
Hypertension (36 papers, 2005 to 2025). The presence of chronic increased pressure in the systemic arterial system. "CYP3A5 is an important gene whose association with hypertension has been established in several studies and has also been linked to salt sensitivity." (PMID 38633331, 2023). "Our results suggest that the GG genotype for rs2242480 in CYP3A4 and CC genotype in rs776746 for CYP3A5 were both associated with the presence of hypertension." (PMID 36982571, 2023). "We observed that at genotype level, the rs2242480 in CYP3A4 (GG) and the rs776746 in CYP3A5 (CC) were significantly associated with the presence of hypertension (p = 0.02)." (PMID 36982571, 2023). "Current results regarding the association between the CYP3A5 genotype and BP/hypertension have been inconsistent." (PMID 36145503, 2022). "A previous study showed that there existed a significant association between rs776746 polymorphism of CYP3A5 and hypertension in Chinese Han population." (PMID 36105185, 2022). "Pharmacogenetic studies have reported inconsistent linkages between CYP3A5 expression and hypertension, however, most investigators have considered CYP3A5*1 as active and CYP3A5*3 as an inactive allele." (PMID 33633318, 2021). "This population analysis of CYP3A5*1/*3 has profound implications not only for the susceptibility to diseases, such as hypertension, but also for safer drug administration regimens, assuring better therapeutic responses and fewer side effects." (PMID 32477124, 2020). "CYP3A5 has been intensively explored in the context of the genetic factors contributing to hypertension susceptibility, known to vary widely across different human populations." (PMID 26018448, 2015). "Many candidate gene studies have explored the association between CYP3A5 variants and blood pressure or hypertension in humans." (PMID 23049672, 2011). "Moreover, the CYP3A5*3 variant has been associated with a greater risk of hypertension and increased serum TG (a type of fat that increases the risk of cardiovascular diseases (CVDs))." (PMID 39523378, 2024). "Similarly, the CYP3A5*3 variant has been linked to an increased likelihood of developing hypertension and increased levels of serum TG." (PMID 39523378, 2024). "Thus, the aim of the present study was to determine the frequency of CYP3A5 polymorphisms, and their association with hypertension in Mexican Amerindians." (PMID 32477124, 2020). "Thus, the frequency of CYP3A5*3 varies between groups and seems to depend on ancestry, and CYP3A5*1 decreases the risk of hypertension in Mexican indigenous women." (PMID 32477124, 2020). "Both CYP3A5*1 and *3 have been associated with hypertension." (PMID 32477124, 2020). "Univariate analysis was used to test all the clinical and genetic factors, resulted in four factors that were significantly associated with TSD: whether has hypertension, whether has diabetes, whether taking omeprazole and CYP3A5 genotype." (PMID 28176850, 2017). "However, reports concerning the association of CYP3A5 genetic polymorphism with BP or hypertension have been largely inconsistent in humans." (PMID 23404385, 2013). "Also the intronic CYP3A5 SNP rs776746 has previously been associated with hypertension and salt sensitivity." (PMID 23036011, 2012). "Our global analysis detected the CYP3A5*7 allele as a common damaging 1-bp insertion in the CYP3A5 gene; this gene is involved in sodium transport and has been proposed to play a role in hypertension." (PMID 22322200, 2012). "Furthermore, a latitudinal cline was identified both for the allele frequencies of the SNPs associated with hypertension (CYP3A5, AGT, GNB3), as well as for those associated with the ability to taste phenylthiocarbamide (TAS2R38)." (PMID 18248681, 2008). "As such, it is possible that CYP3A5 rs776746C allele carriers may derive greater benefit from antihypertensive drugs that are CYP3A5 substrates, which also results in reduced occurrence of hypertension-related adverse outcomes such as CKD." (PMID 39063918, 2024).
Hypertension (continued). "A particular allele of the CYP3A5 enzyme that plays an important role in the metabolism of cortisol and corticosterone has been associated in African-American patients with higher systolic blood pressure levels in normotensive participants and hypertension more resistant to treatment." (PMID 24053215, 2013). "In the kidney, CYP3A5 is responsible for the conversion of cortisol to 6-β-hydroxycortisol which enhances sodium and water retention, thereby contributing to hypertension." (PMID 38633331, 2023). "Our findings support this: CYP3A5*3 homozygotes had increased risk of CKD, for which high blood pressure is a risk factor, and were 59% more likely to change treatments compared to common homozygotes." (PMID 36134646, 2023). "Given the limited sample size, additional studies are necessary to investigate the role of CYP3A5 in the regulation of BP and the pathogenesis of hypertension." (PMID 36145503, 2022). "Three hypertension susceptibility genes—AGT, CYP3A5 and GNB3—have been suggested to have undergone natural selection, providing a new way to study genetic susceptibility to hypertension." (PMID 33777100, 2021). "Nifedipine, frequently prescribed for hypertension, is a competitive CYP3A5 inhibitor which can inhibit tacrolimus metabolism." (PMID 34290611, 2021). "Given the importance of CYP3A5*3 in drug response and hypertension development, the aim of the present study was to evaluate the frequency of this polymorphism and its association with hypertension in vulnerable indigenous populations in Mexico." (PMID 32477124, 2020). "There are many confounding factors such as ethnicity, the modulating effect of salt intake, and concomitant hypertension medications, some of which are CYP3A5 substrates." (PMID 33182477, 2020). "Hypertension, use of omeprazole, and CYP3A5 genotype were used to construct the multiple linear regression (MLR)." (PMID 32596403, 2020). "SNP rs776746 in CYP3A5 GG were less likely to experience hypertension when compared with the AA or AG carriers (OR 0.3, 95% CI 0.1–0.9, p = 0.05)." (PMID 29581831, 2018). "The PTV rs2884737 in VKORC1 associated with hypertension is in moderate LD (R2 ≈ 0.56) with several nearby common variants and the PTV rs776746 in CYP3A5 associated with hayfever/allergic rhinitis is in near perfect LD with one other nearby variant." (PMID 29691392, 2018). "The remaining three factors (hypertension, use of omeprazole and CYP3A5 genotype) were used to construct the MLR and 8 machine learning models." (PMID 28176850, 2017). "It is notable that all three; normal homozygotes (CYP3A5*1/*1), hypertension and salt sensitivity are simultaneously higher in African Americans." (PMID 23404385, 2013). "It has been shown that the adverse reactions of TKI correlate with drug concentrations and metabolic enzyme gene polymorphisms, such as CYP3A5*3 for sorafenib-related severe hepatic and renal damage, and CYP3A4-rs4646437 and CYP3A5-rs776746 for sunitinib-related hypertension." (PMID 35814206, 2022). "Because some MR ligands generated by CYP3A5 promote sodium retention, renal CYP3A5 inhibition strategies may be appropriate for treating hypertension." (PMID 33633318, 2021). "However, attempts to establish a link between CYP3A5 genotype and hypertension in humans have yielded inconsistent outcomes." (PMID 33633318, 2021). "The CYP3A5*3/*3 genotype is more frequent in women with hypertension." (PMID 34948113, 2021). "The frequency of the CYP3A5*3 allele is significantly correlated with distance from the equator and has similar geographic distribution than the AGT M235T, a variant associated with blood pressure and hypertension." (PMID 23049672, 2011). "Carriers of CYP3A5*1 may have diminished pharmacological effect of verapamil, a nondihydropyridine calcium channel blocker that can be used to treat hypertension." (PMID 23049672, 2011).
Hypertension (continued). "Transcriptional CYP3A5 amplification from stress-induced release of glucocorticoids and salt intake, combined with salt retention, and vitamin D hormone insufficiency, can all contribute to hypertension via modulation of the renin–angiotensin–aldosterone-system (RAAS)." (PMID 33633318, 2021). "Currently, the distribution of the CYP3A5*3 polymorphism in Mexican indigenous groups is unknown, and the association of the CYP3A5 gene with hypertension has not been reported." (PMID 32477124, 2020). "Furthermore, considering the hypertension-associated SNPs, whilst the Kashmiri group had a significantly lower MAF for the CYP3A5 g.6980G>A SNP compared to the other groups, this language group also had the highest MAF for the AGT g.802C>T SNP and the second highest MAF for the GNB3g.4423C>T SNP." (PMID 18248681, 2008). "Since the CYP3A5*3, *6, and *7 variants lead to a non-functional CYP3A5 enzyme, individuals carrying these variants may have reduced cortisol metabolism and sodium retention, potentially reducing their risk of hypertension compared to CYP3A5*1 carriers." (PMID 40463714, 2025). "In GWAS analysis, the genes CYP3A5, SLC24A3 and CTSA are observed in obesity related diseases like Hypertensive disease, Asthma, Coronary Artery Disease, Essential Hypertension, Hypertensive disease and Heart failure." (PMID 32027667, 2020). "As a secondary analysis, we also hypothesized that genetic variation in ADRB1, CYP3A5, and NEDD4L genes may explain BP variation in hypertension." (PMID 39063918, 2024). "In a meta-analysis, there was no overall effect of CYP3A5 expressor status on BP or hypertension." (PMID 33182477, 2020). "Furthermore, the CYP3A5 locus did not come out in GWAS for blood pressure and hypertension." (PMID 23049672, 2011). "Also, considering risks of arterial constriction, hypertension, and renal toxicity that may develop with supra therapeutic concentrations of TAC, dose adjustment based on observed serum concentrations should be made for intermediate (CYP3A5*1/*3) or rapid (CYP3A5*1/*1) metabolizers using TDM." (PMID 35935867, 2022).
breast carcinoma (19 papers, 2007 to 2023). "In postmenopausal tamoxifen-treated breast cancer patients, a genetic polymorphism in CYP3A5 (CYP3A5*3) was found to be correlated with a positive response." (PMID 33809117, 2021). "Similar to the findings, hydrogen bonding was also observed between lapatinib (oral tyrosine kinase inhibitor used for breast cancer and tumours that may cause hepatotoxicity) and Thr309 in CYP3A5." (PMID 36518400, 2022). "Tucker and colleagues recently tested whether genetic polymorphisms in CYP3A5 were associated with altered metabolism of tamoxifen in patients with breast cancer." (PMID 17244352, 2007). "In this population-based cohort of premenopausal breast cancer survivors with non-distant metastatic breast cancer, homozygous carriers of CYP3A5 rs776746 had delayed return-to-work and stable labor market attachment after breast cancer." (PMID 36598552, 2023). "DMI—a component of the trastuzumab–DMI conjugate used in the treatment of high-risk early stage and metastatic HER-2-positive breast cancer, is metabolised by CYP3A4 and to a lesser extent by CYP3A5." (PMID 33809117, 2021). "CYP3A5 is commonly expressed in HER-2-positive breast cancers and is reported to be involved in the bioactivation of lapatinib." (PMID 33809117, 2021). "Frequency of CYP3A4*1B, CYP3A5*3 and UGT1A4*2 SNPs in 126 Croatian breast cancer (BC) patients and possible association with anastrozole-induced undesirable side effects were analyzed." (PMID 32456253, 2020). "We studied the association of the functionally significant variant alleles of CYP3A4, CYP3A5, CYP2B6, CYP2C8, CYP2C9 and CYP2C19 with the clinical response to neoadjuvant chemotherapy in breast cancer patients." (PMID 22702493, 2012). "Here, we studied the association of functionally significant variant alleles of CYP3A4, CYP3A5, CYP2B6, CYP2C8, CYP2C9 and CYP2C19 with the clinical response to neoadjuvant chemotherapy in breast cancer patients." (PMID 22702493, 2012). "The CYP3A5 non-expressing variant has been associated with reduced risk of neurotoxicity during treatment in 118 Spanish cancer patients (1/3 breast cancer) treated with paclitaxel, corresponding to an increased risk in expressors." (PMID 36598552, 2023). "In the present study, we investigated the pharmacokinetics profile and the influence of CYP2D6, CYP2C9, CYP2C19, CYP3A5, POR, ABCB1 and UGT2B15 polymorphisms on the plasma level of tamoxifen and its active metabolites in Ethiopian breast cancer patients receiving adjuvant tamoxifen." (PMID 31547390, 2019). "We have reported the diversity of polymorphism frequencies for the CYP2D6, CYP3A5, CYP2C8, and IL-10 genes in breast cancer patients from Mexico and Spain and classified them by metabolic activity for chemotherapy but no specific function has been described for these polimorphisms." (PMID 29997359, 2018). "Thus, CYP3A5*3 and CYP2C19*2 seem to be beneficial with regards to the risk of recurrence or to breast cancer-specific survival, respectively." (PMID 23346096, 2012). "In the present study we investigated the prognostic and/or predictive value of functional polymorphisms in cytochrome P450 3A5 CYP3A5 (*3), CYP2D6 (*4), sulphotransferase 1A1 (SULT1A1; *2) and UDP-glucuronosyltransferase 2B15 (UGT2B15; *2) in tamoxifen-treated patients with breast cancer." (PMID 17244352, 2007). "In addition, assessment of CYP3A4, CYP3A5 and UGT1A4 variant alleles and knowledge about their allelic frequency in the Croatian population may lead to personalized breast cancer therapy." (PMID 32456253, 2020). "Increased docetaxel-induced adverse events were also observed in breast cancer patients who were CYP3A4*22 carriers and CYP3A5*3 homozygotes." (PMID 35174070, 2021). "In this descriptive study, correlations were examined between concentrations of tamoxifen metabolites and genotypes for CYP2D6, CYP3A4, CYP3A5, SULT1A1, SULT1A2 and SULT1E1 in 135 patients with estrogen receptor-positive breast cancer." (PMID 23922954, 2013).
breast carcinoma (continued). "Germ line DNA samples from 230 patients with breast cancer on AC therapy were genotyped for the following SNPs: ABCB1 C1236T, G2677T/A and C3435T, SLC22A16 A146G, T312C, T755C and T1226C, CYP2B6*2, *8, *9, *3, *4 and *5, CYP2C9*2 and *3, CYP3A5*3 and CYP2C19*2." (PMID 20179710, 2010).